MIR548AS (microRNA 548as)
Synonyms: hsa-mir-548as
Gene: MicroRNA gene on chromosome 13 (92,490,163 to 92,490,220, forward strand). Ensembl gene ENSG00000263741.
Homologues: Orthologues: chimpanzee MIR548AS (98% identical). Paralogues in human: MIR548K (83% identical), MIR548AA1 (78% identical), MIR548AZ (78% identical), MIR548AQ (76% identical), MIR548H5 (76% identical), MIR548S (76% identical), MIR548X2 (76% identical), MIR548AJ1 (74% identical), MIR548AX (74% identical), MIR548N (74% identical), MIR548X (74% identical), MIR548H3 (72% identical), and 13 more.